IRF5 (interferon regulatory factor 5)
Diseases named in the same sentence as IRF5 in open-access papers (continued):
Sharing a sentence is not in itself a finding about the gene and the disease.
breast carcinoma (14 papers, 2011 to 2025). "Pimenta and colleagues reported that loss of IRF5 in breast cancer cells leads to dysregulation of cytokines and chemokines, subsequently impairing immune cell recruitment to tumor sites." (PMID 41179282, 2025). "IRF5 is a transcription factor and its loss increases the motility and contributes to the activation of the metastatic behaviour of breast cancer cells." (PMID 34771489, 2021). "Given the small sample size, it was difficult to make statistical correlations between receptor and IRF expression; however, data at present suggest that loss of IRF5 expression correlates with ER/PR(-) breast cancers in 82 to 90% of samples." (PMID 22053985, 2011). "We demonstrated that loss of IRF5 expression correlated with advanced stages of breast cancer and invasion/metastasis." (PMID 22053985, 2011). "Here, we examined the expression of IRF5 in primary breast tissue and determined how loss of expression may contribute to breast cancer development and/or progression." (PMID 22053985, 2011). "Subsequent network pathway clustering analysis of these genes revealed that tryptophan metabolism occupies a central role among the IRF5-associated biochemical processes, suggesting that IRF5 may influence distant metastasis of breast cancer through the tryptophan metabolic pathway." (PMID 41179282, 2025). "Analysis of data from The Cancer Genome Atlas (TCGA) showed that IRF5 expression was significantly elevated in breast cancer tissues relative to normal breast tissue." (PMID 41179282, 2025). "Collectively, these results indicate that IRF5 promotes tryptophan metabolism in breast cancer cells and facilitates metastasis by transcriptionally upregulating SLC7A5 and IDO1." (PMID 41179282, 2025). "We conducted a comprehensive analysis of differential IRF5 expression in breast cancer metastatic sites, identifying 421 differentially expressed genes, including 226 upregulated and 195 downregulated genes." (PMID 41179282, 2025). "Compared to normal mammary epithelial MCF10A cells and other breast cancer subtypes, IRF5 expression was markedly upregulated in TNBC cell lines." (PMID 41179282, 2025). "For instance, In osteosarcoma and breast carcinoma cells with high IRF5 expression, tumor-derived EVs are less secreted and altered in composition, reducing their pro-metastatic potential." (PMID 40103824, 2025). "Analysis of breast cancer data from the TCGA database revealed a strong positive correlation between IRF5 expression and that of SLC7A5 and IDO1." (PMID 41179282, 2025). "Immunohistochemical analysis of breast cancer samples further confirmed pronounced IRF5 overexpression in all TNBC tumor tissues." (PMID 41179282, 2025). "Then, we analyzed IRF5 expression across various breast cancer cell lines, with a focus on TNBC lines, using qRT-PCR." (PMID 41179282, 2025). "In this regard, the TFs IRF-1 and IRF-5 have been shown to act as tumor suppressors in breast cancer." (PMID 34367349, 2021). "Previous studies showed that IRF5 changed the immune microenvironment of tumors by regulating the expression of pro-inflammatory and anti-inflammatory cytokines/chemokines in breast cancer." (PMID 32528869, 2020). "Not surprising given its known immunoregulatory functions, recent data also support an important extrinsic role for IRF5 in human breast cancer progression through its ability to regulate the tumor-immune microenvironment." (PMID 25649192, 2015). "Using data from The Cancer Genome Atlas (TCGA) of all human primary breast cancers (n = 3,455), we performed a correlation analysis with IRF5 transcript expression and recurrence-free survival (RFS)." (PMID 25649192, 2015). "In a 3-dimensional (3D) in vitro model of invasive breast cancer cell growth, overexpression of IRF5 in MDA-MB-231 cells resulted in a complete reversal of invasive acini outgrowth to normal ductal structure." (PMID 25649192, 2015).
breast carcinoma (continued). "Together, these data show that IRF5 inhibits breast cancer metastasis primarily through its negative regulation of mammary epithelial cell migration." (PMID 25649192, 2015). "Further studies will be necessary to address the question of how or why IRF5 expression is altered in different stages of human breast cancer." (PMID 22053985, 2011). "Overexpression of IRF5 in breast cancer cells inhibited in vitro and in vivo cell growth and sensitized them to DNA damage." (PMID 22053985, 2011). "IRF1 and IRF5 expression were examined in FFPE specimens from patients with different stages of breast cancer by IF and IHC." (PMID 22053985, 2011). "Here we show that expression of the transcription factor interferon regulatory factor 5 (IRF5) in osteosarcoma (OS) and breast carcinoma (BC) clinically correlates with prolonged survival and decreased secretion of tumor-derived extracellular vesicles (t-dEVs)." (PMID 38969706, 2024). "Additionally, IRF5 expression is decreased in breast cancer tissues, and overexpression of IRF5 in breast cancer cell lines results in DNA damage-induced cell death and tumor suppression." (PMID 29438328, 2018). "While IRF5 is known to be immunomodulatory in most cell types, the xenograft studied was done in immunocompromised mice indicating that IRF5 expression in breast cancer cells intrinsically changes their cellular function conferring a less invasive and metastatic phenotype." (PMID 25649192, 2015). "In this study, we significantly extend our original findings to further delineate the mechanism(s) by which IRF5 controls breast cancer cell growth and metastasis and ultimately find that IRF5 may be a global regulator of epithelial cell migration." (PMID 25649192, 2015). "MCF-7 breast cancer cells express a moderate amount of endogenous IRF5 and are minimally invasive." (PMID 25649192, 2015). "IRF5 was mapped to chromosome 7q32 that contains a cluster of imprinted genes and/or known chromosomal aberrations and deletions in lymphoid, prostate, and breast cancer." (PMID 22053985, 2011). "Since these data suggested that IRF5 may contribute to the regulation of CXCR4 in breast cancer cells, we performed a computer-based analysis of the human CXCR4 gene promoter with MatInspector; two IRF binding elements (IRF-E) were identified." (PMID 22053985, 2011). "Furthermore, IRF5 is part of a 28-gene signature for predicting breast cancer recurrent and metastatic potential." (PMID 22053985, 2011). "FBXL8 downregulation increased accumulation of CCND2 and IRF5 and reduced the cancer-promoting chemokines, modulated TME, leading to repressing tumor metastasis in breast cancer." (PMID 36733484, 2023). "IRF5, MAP2K2 (MEK2), and S100P had concordant overexpressed mRNA in invasive breast cancer tissues and blood samples." (PMID 37445737, 2023). "We found that the expression of SIRT7 was positively correlated with the expression of IRF5 (M1 macrophages marker) and PD1 (PDCD1) (T cell exhaustion marker) in breast cancer-luminal." (PMID 32528869, 2020). "Most DCIS breast cancers retained expression of IRF1 in tumor tissue with 23 out of 24 staining positive, whereas IRF5 expression was significantly reduced with only 9 out of 24 staining positive." (PMID 22053985, 2011). "Sirt7 is high expressed in breast cancer, which is an indicator of poor prognosis, and the expression of Sirt7 is positively correlated with the expression of IRF5 and PD1, which increases M1 macrophages, and depletes T cells in the immune environment of breast cancer." (PMID 34880761, 2021). "Furthermore, our IHC staining of breast carcinoma tissues demonstrated a reciprocal profile of FBXL8 versus CCND2 and IRF5 with cancer advancement over stages I–III." (PMID 32784654, 2020). "We have identified for the first time a non-transcriptional and cytoplasmic function for IRF5 that inhibits breast cancer cell migration." (PMID 25649192, 2015).
breast carcinoma (continued). "The fact that IRF5 is well expressed in immortalized non-oncogenic mammary epithelial cells compared to breast cancer cells and tumor tissues is consistent with the concept that IRF5 is a tumor suppressor protein." (PMID 22053985, 2011). "Additionally, IRF5 downregulation significantly decreased levels of kynurenine (KYN), a tryptophan metabolite, within these breast cancer cells, further supporting the notion that IRF5 modulates breast cancer cell function via regulation of tryptophan metabolism." (PMID 41179282, 2025). "Additionally, in a xenograft nu/nu mouse model using two different breast cancer cell lines made to stably express IRF5, no metastasis was found in mice injected with IRF5-positive tumors compared to metastasis in control cohorts that lacked intratumoral IRF5 expression." (PMID 25649192, 2015).
asthma (13 papers, 2013 to 2025). "Single nucleotide polymorphisms in Rgs2, and IRF5 activity have been associated with asthma and our data highlighted upregulated transcription of these genes in HDM-stimulated ILC2s." (PMID 29250067, 2017). "It was shown that a common IRF5 gain-of-function haplotype is associated with asthma and the severity of asthmatic symptoms." (PMID 23533311, 2013). "We quantified macrophage subsets in bronchial biopsies of asthma patients using interferon regulatory factor 5 (IRF5)/CD68 for Th1-associated macrophages, CD206/CD68 for Th2-associated macrophages and interleukin 10 (IL10)/CD68 for anti-inflammatory macrophages." (PMID 35387061, 2021). "IRF5 polymorphisms were also recently identified that associate with asthma and its severity." (PMID 30515152, 2018). "In particular, male patients with asthma have a relatively greater number of IRF5+ M1 macrophages, and female patients with asthma have a greater number of CD206+ M2 macrophages." (PMID 35625578, 2022). "We found that patients with neutrophilic asthma and low FEV1 had the most IRF5+ macrophages of all asthma subgroups, which was significantly different from patients with mixed eosinophilic asthma and patients with neutrophilic asthma and normal FEV1." (PMID 35387061, 2021). "Although IRF5−/− mice subjected to the severe asthma model displayed lower IFNγ and IL-17 responses and lower neutrophil numbers, they had higher Th2 responses with higher eosinophil numbers." (PMID 29572536, 2018). "Additional work in both human and mouse models of asthma and allergic airway inflammation suggests an important role for Irf5 in driving disease severity." (PMID 30515152, 2018). "Both, especially IRF5, have been extensively related to asthma regulation." (PMID 41154593, 2025). "This study shows that neutrophilic asthma with low FEV1 is associated with high numbers of IRF5+, and low numbers of IL10+ macrophages, which may be the result of combined effects of smoking and having asthma." (PMID 35387061, 2021). "In conclusion, our study has shown that neutrophilic asthma with low FEV1 is associated with high numbers of IRF5+, and low numbers of IL10+ macrophages, which may be the result of the combined effects of smoking and having asthma." (PMID 35387061, 2021). "The peptide inhibitors or small molecules that block the Lyn–IRF5 interaction could be used in the context of asthma to enhance IRF5 function." (PMID 30199605, 2019). "Additionally, IRF5 drove a Th1 cell response and airway hyperreactivity in severe asthma mice." (PMID 39384770, 2024). "Therefore, peptide inhibitors that block the Lyn–IRF5 interaction could be used in the context of asthma to enhance IRF5 function." (PMID 30199605, 2019). "However, inhibition of M2 polarisation as a therapeutic intervention for asthma has unfortunate consequences as this shifted the balance towards more IRF5+ M1 macrophages and neutrophilic lung inflammation and the development of more severe airway hyperresponsiveness." (PMID 29572536, 2018). "Asthma patients had significantly more CD206+ (p = 3.9E-17) and IRF5+ (p = 1.9E-17), and fewer IL10+ macrophages (p = 3.1E-15) than healthy individuals." (PMID 35387061, 2021). "In murine asthma models with house dust mite (HDM) exposure, Irf5−/− demonstrate impaired lung function and extracellular matrix deposition, but mice overexpressing IRF5 were protected from allergic inflammation." (PMID 30199605, 2019). "These associations were more pronounced in nonatopic asthmatics, and it was suggested that IRF5 may only have a profound impact on the pathogenesis and severity of nonatopic asthma and not on atopic asthma." (PMID 23533311, 2013). "Finally, SNPs that were molecular QTLs in our study colocalized with asthma GWAS SNPs, revealing 46 unique colocalizations that included both known asthma loci (e.g., 17q12-21 and TSLP) and loci that did not meet stringent criteria for genome-wide significance in the GWASs (e.g., IRF5 and PMM1)." (PMID 34629083, 2021).
Sjögren’s syndrome (13 papers, 2010 to 2026). "IRF5 polymorphisms have been connected to elevated production of pro-inflammatory cytokines and type I interferons in Sjögren’s syndrome, which has been implicated in the development of systemic characteristics and an elevated risk of lymphoma." (PMID 40321894, 2025). "Mucosa-associated lymphoid tissue (MALT) lymphoma is considerably more likely to occur in patients with Sjögren’s syndrome and high IRF5 expression, according to clinical research." (PMID 40321894, 2025). "NHL and Sjögren’s syndromeBCL2 (NHL) and IRF5 (Sjögren’s Syndrome) a potential cross-pathway interaction is suggested by the connection between BCL2’s role in apoptotic control in NHL and IRF5’s role in the immunological response in Sjögren’s syndrome." (PMID 40321894, 2025). "IRF5 has been shown to play critical roles in immune responses and is involved in the pathogenesis of several immune diseases, including SLE, Sjögren’s syndrome, and psoriasis." (PMID 41007813, 2025).
Arthritis (12 papers, 2009 to 2025). Inflammation of a joint. "IRF5 expression polarizes macrophages toward an inflammatory state, and elevated IRF5 levels have been implicated in age-related conditions such as arthritis and glioma." (PMID 40493408, 2025). "A recent study showed that TLR7 deficiency alleviated K/BxN serum-induced arthritis by imparing interferon regulatory factor 5 (IRF5) mediated IL-1β and IL-6 produced by macrophages and synovial fibroblasts, respectively." (PMID 34950033, 2021). "A recent study also showed that TLR7 deficiency led to K/BxN serum-induced arthritis reduction by imparing interferon regulatory factor 5 (IRF5) mediated IL-1β and IL-6 generation in macrophages and synovial fibroblasts, respectively." (PMID 34950033, 2021). "Genetic deficiency of IRF5 in an arthritis animal model could reduce arthritis severity." (PMID 32290250, 2020). "The proinflammatory role of IRF5 was also confirmed in vivo, for example, IRF5—deficient (IFR5−/−) mice exhibit significantly reduced joint damage in arthritis models." (PMID 41155224, 2025). "IRAK4i therapy markedly attenuated arthritis by inhibiting IRF5, M1 gene transcription, and Th1/Th17 cell differentiation." (PMID 37158847, 2023). "In the antigen-induced model of arthritis, a population of Irf5-positive pro-inflammatory macrophages was found to significantly increase in inflamed knees, suggesting that IRF5 can be used as a marker of inflammatory macrophages in a disease setting." (PMID 30515152, 2018). "Moreover, we identified EFL2 as an effective IRF5 inhibitor to block the inflammatory responses during arthritis development." (PMID 34950033, 2021). "Depletion of IRF5 is able to protected mice from methylated BSA-induced acute arthritis or K/BxN serum transfer arthritis, suggesting that IRF5 could be an attractive therapeutic target in arthritis." (PMID 34950033, 2021).
melanoma (11 papers, 2012 to 2026). A malignant, usually aggressive tumor composed of atypical, neoplastic melanocytes. "In conclusion, polymorphism of IRF-5 appears to be a predictor of immune responsiveness of melanoma metastases to adoptive therapy with TILs." (PMID 22909381, 2012). "This is the first study analyzing the role of IRF5 gene polymorphism in determining immune responsiveness of melanoma." (PMID 22909381, 2012). "This study is the first to analyze associations between melanoma immune responsiveness and IRF5 polymorphism." (PMID 22909381, 2012). "Therefore, we investigated whether polymorphisms in IRF5 associated to SLE are also associated with melanoma responsiveness to immunotherapy." (PMID 22909381, 2012). "Meanwhile, nanoparticles encoding mRNA for interferon regulatory factor 5 (IRF5) significantly reduced tumor progression in ovarian cancer, melanoma lung metastasis, or glioblastoma models." (PMID 39310113, 2024). "To measure anti-tumor responses in a clinically relevant in vivo test system, we administered particles containing IRF5/ IKKβ mRNA into mice with disseminated pulmonary melanoma metastases." (PMID 31481662, 2019). "Melanoma patients with the IRF5 SNP considered protective against SLE were more likely to be non-responsive to immunotherapy treatments." (PMID 24762633, 2014). "K-means clustering algorithm, performed on the class comparison of metastases based on transcripts differentiating melanoma cell lines with distinct IRF5 genotype, segregated two groups of patients." (PMID 22909381, 2012). "Interestingly, as was the case with the LTA gene, certain SNPs in IRF5 have been identified in patients with melanoma." (PMID 24762633, 2014). "When genes differentiating melanoma cell lines in vitro according to genotype were applied for class prediction, a segregation of responding and non responding cases was observed and it was only partially predictive of the IRF5 genotype in vivo." (PMID 22909381, 2012). "Nine of the 15 cell lines generated from the melanoma metastases were analyzed for functional differences according to their IRF5 genotype; the genetic profile of these cell lines and its relationship with the parental tumors has been extensively described elsewhere." (PMID 22909381, 2012). "Remarkably, transcriptional changes observed between melanoma cell lines carrying or not the A allele could be used to predict responsiveness of 112 melanoma metastases (MM), suggesting that the IRF5-dependent immune responsiveness is at least partly related to the intrinsic biology of melanoma." (PMID 22909381, 2012). "PRELPhigh melanoma cells express increased levels of NLRC5 as well as selected IFN-γ signal transduction molecules, e.g., IRF1, IRF5, STAT1 and STAT2." (PMID 37730606, 2023). "However, to our knowledge, IRF5 polymorphisms have never been studied in the context of melanoma." (PMID 22909381, 2012). "Interestingly, we observed significant downregulation of the IRF transcription factor family members (IRF1, IRF2, IRF5, IRF8) corresponding to attenuated interferon signaling in TRIM28HIGH melanomas, probably as a consequence of low immune cell infiltration." (PMID 33076560, 2020).
systemic sclerosis (11 papers, 2011 to 2024). A chronic disorder, possibly autoimmune, marked by excessive production of collagen which results in hardening and thickening of body tissues. "Furthermore, IRF5 polymorphism increases the risk of systemic sclerosis whereas reduced expression of IRF5 increases survival." (PMID 34650521, 2021). "Indeed, deletion of IRF5 protected mice from development of bleomycin-induced skin and pulmonary fibrosis, which makes IRF5 a potential therapeutic target in systemic sclerosis and scleroderma." (PMID 34650521, 2021). "Thus, the intriguing possibility that CB1R-mediated IRF5 signaling may contribute to skin and pulmonary fibrosis development in systemic sclerosis and scleroderma, needs to be explored in future studies." (PMID 34650521, 2021).